AR (androgen receptor)
Diseases named in the same sentence as AR in open-access papers (continued):
Sharing a sentence is not in itself a finding about the gene and the disease.
tumor (continued). "The C-terminal acidic domain (CAD) of TSPX is crucial for the tumor suppressor functions, such as inhibition of cyclin B/CDK1 phosphorylation and androgen receptor transactivation." (PMID 30863497, 2019). "This provides evidence that ATTs, in this case castration, can activate a global program of EMT in PCa castrate-resistant tumours, which is dynamically regulated during progression to CRPC via the reactivation of AR/androgen-signalling and promotion of MErT." (PMID 30194451, 2019). "A clear separation between ER+ BRCA/AR+ TNBC and PRAD tumor samples is observed in the space of the first two principal components, though partial overlap is observed when looking at PCs individually." (PMID 31238876, 2019). "The tumours fall into the three expected groups: MA tumours (AR high and ESR1 low) in the upper left quadrant, basal-like tumours (AR low and ESR1 low) in the lower left quadrant and luminal tumours (AR high and ESR1 high) in the upper right quadrant." (PMID 30899086, 2019). "The MFB tumor cells show immunoreactivity for CD34, desmin, and, variably, with smooth muscle actin (SMA), estrogen receptor (ER)/progesterone/androgen receptor, CD99, B-cell lymphoma 2 (Bcl2), and CD10, and they do not express cytokeratins or p63." (PMID 30989009, 2019). "In contrast to above results, knocking down endogenous LRIG1 using pGIPZ-shLRIG1 in 3 AR+, AD PCa cells, VCaP, LAPC4, and LAPC9, significantly promoted tumor regeneration." (PMID 31792211, 2019). "Nonetheless, they observed elevated expression of KDM4B, XBP1, AR, MYB, and SPDEF in early neoplasias compared to normal which were also elevated in our profile." (PMID 31248446, 2019). "Second, most drugs, which showed synergistic effects with BH3 mimetics, target signaling pathways, e.g., androgen receptor (AR) or receptor tyrosine kinase (RTK) pathways, that are altered in advanced tumor stages." (PMID 31312616, 2019). "AR, CCRK, and β-catenin were found to concordantly overexpress in the tumor cells in primary human HCC tissue samples." (PMID 31027362, 2019). "This tumor line grows subcutaneously in wildtype C57BL/6J immunocompetent mice, expresses AR, and has a luminal cytokeratin profile." (PMID 31839878, 2019). "Certain NRs are clearly consistently observed across different tumor types; for instance, VDR, PPARs, ER, GR and AR in CAFs, as well as GR and PPARs in TAMs and endothelial cells." (PMID 30925918, 2019). "Sparse logistic regression models were built independently for ER+ BRCA, AR+ TNBC and PRAD data for the classification of patients into tumor or normal tissue." (PMID 31238876, 2019). "Functional studies reveal strong tumor-suppressive functions of LRIG1 in both AR+ and AR− xenograft models, and transgenic expression of LRIG1 inhibits tumor development in Hi-Myc and TRAMP models." (PMID 31792211, 2019). "A Principal Component Analysis (PCA) was applied to a dataset comprising gene expression data from ER+ BRCA, AR+ TNBC and PRAD tumor tissue samples, along normal tissue samples from breast and prostate patients." (PMID 31238876, 2019). "In addition, in patients with metastatic CRPC, the presence of detectable AR-V7 transcripts in circulating tumor cells has been associated with a high positive predictive value for a non-response to AR-targeting agents, including enzalutamide, in several studies." (PMID 30935141, 2019). "Resveratrol has also been shown to down-regulate AR expression in TRAMP mouse models, and alter the AR and chemokine receptor type 4 (CXCR4) pathways required for tumour progression and metastasis." (PMID 31540470, 2019). "Prognosis of AR positive tumours within TNBC appears conflicting; studies have shown lower chemotherapy response rates in AR expressing tumours, likely due to the lower Ki67 rate in these tumours." (PMID 31769425, 2019). "We found that the simultaneous inhibition of AR and PDEF expression dramatically inhibited tumour growth and considerably reduced Ki67 and MYC expression." (PMID 30217192, 2018).
tumor (continued). "They showed that resveratrol inhibits AR–stimulated proliferation by activating SIRT1 in vitro, and that SIRT1 overexpression in xenograft model BALB/c mice represses tumor growth in vivo." (PMID 30380732, 2018). "Our results support the evidence of those studies, showing that BC tumor with high mRNA level of FOXA1 are generally ER and AR enriched." (PMID 29970021, 2018). "Ongoing studies are investigating how heterogeneity in AR distribution, e.g., largely cytoplasmic AR in LAPC4 CRPC, impacts tumor response to antiandrogens." (PMID 30190514, 2018). "BAT is exploiting the adaptive increase of AR levels in CRPC, allowing the tumor cells to cope with castrate levels of testosterone, by rapidly cycling between androgen stimulation and deprivation." (PMID 30382692, 2018). "Therefore, the following features of rhizochalinin and its derivates were determined: i) main mechanisms of drug-induced tumor suppression, such as cytotoxic action, antiproliferative activity, and apoptosis induction; ii) inhibition of pro-survival autophagy and iii) inhibition of AR signaling." (PMID 29682197, 2018). "In our study, patients with AR + /FOXA1 + tumours had a shorter RFS and OS than other TNBC and AR/FOXA1 co-expression was an independent prognostic factor for OS." (PMID 29880907, 2018). "There were significant differences of tumor volume between MCF7 expressing control and shRNA against AR groups." (PMID 29423076, 2018). "Among patients with a PD-L1 + tumour, we found significantly poorer RFS and OS in case of AR/FOXA1 co-expression." (PMID 29880907, 2018). "RFS was significantly shorter for AR + /FOXA1 + tumours compared with other tumours (AR + /FOXA1- and AR-) (p = 0.020)." (PMID 29880907, 2018). "Inhibition of ACK1 with a small molecule inhibitor confirms that this epigenetic activity is required to maintain AR transcription and CRPC tumor growth." (PMID 29888169, 2018). "While absolute AR expression levels were quite normal, we observed a slight increase in both p300 and the CREB-binding protein CBP in C5 tumor material (RNA-seq)." (PMID 30510249, 2018). "Among patients with a PD-L1 + tumour (N = 145), RFS (p = 0.012) and OS (p = 0.002) were shorter in case of AR/FOXA1 co-expression." (PMID 29880907, 2018). "Here, the authors demonstrate that BMI1 directly interacts with AR leading to increased AR signaling independently of PRC1 complex and that targeting BMI1 inhibits tumor growth of castration-resistant prostate cancer tumors." (PMID 29402932, 2018). "Myc-CaP PTEN KO cells contained increased phosphorylated-AKT and androgen receptor, and expressed approximately 2-fold higher levels of PD-L1, PD-L2, CD95, and CD95L, all important in tumor immune-evasion." (PMID 29686284, 2018). "We established CRPC a xenograft tumor model VCaP-CRPC, based on the castration-relapse growth of AR-positive and androgen-responsive VCaP cells in castrated host severe combined immunodeficiency (SCID) mice." (PMID 29555975, 2018). "AR + /FOXA1- and AR- tumours more frequently exhibited a staining of > 50% of TILs, compared to AR + /FOXA1 + tumours (10–50% of stained TILs more frequent)." (PMID 29880907, 2018). "This occurs through a recruitment of AR at ARE localized in ERβ promoter and lastly inhibits cancer cell growth, as ERβ prevalently acts as a tumor suppresson in BC." (PMID 30210453, 2018). "The values are the mean total AR positive cells per tissue area (μm2) ± SEM in prostate epithelium, hyperplasia or tumor." (PMID 28493878, 2017). "Lysine-specific demethylase 1A (LSD1) is a key regulator of the androgen (AR) and estrogen receptors (ER), and LSD1 levels correlate with tumor aggressiveness." (PMID 28811844, 2017). "It is not until tumors are treated with a combination of JQ1+Enz together do we see inhibition of both AR and GR signaling pathways, as well as LREX' tumor regression." (PMID 28891793, 2017).
tumor (continued). "It highlights the importance of further research elucidating the AR pathway in AAC, for which androgen represents the known steroid hormone stimulating tumor growth." (PMID 28445946, 2017). "Inhibition of AR signaling significantly reduces TNBC cell proliferation, migration, invasion and increases apoptosis in vitro, while significant reduction of tumor viability is reported by AR inhibition in vivo." (PMID 29099049, 2017). "When the CR tumor cells were injected into SCID mice, the expression of luminal markers (AR, NKX3.1) increased significantly, while basal cell markers dramatically decreased." (PMID 28009986, 2017). "After treatment with berberine, the levels of PSA, AR, COX-2, Bcl-2 in tumor tissues were markedly decreased, and the expression of Caspase-3 was increased." (PMID 29029409, 2017). "Where mice were implanted with initiated epithelium and AR positive UGM, tumour formation occurred in 36% (n = 30/84) of hormone treated mice but <0.5% (n = 1/218) of untreated mice." (PMID 28117763, 2017). "AR, androgen receptor; CI, confidence interval; CN, copy number; MTV, metabolic tumor volume; N, number; OS, overall survival; PFS, progression-free survival; TLA, total lesion activity." (PMID 29138500, 2017). "Most tumours initially show response to androgen deprivation therapy (ADT), while remaining AR-positive and further responsive to AR-signalling." (PMID 28241429, 2017). "AR is highly expressed in ER− BCa and the functional crosstalk between AR and HER2 is critical for the tumor cell survival and expansion." (PMID 28134791, 2017). "Although the exact role of ARs in TNBC remains to be elucidated, current research indicates that AR is highly conserved throughout TNBC progression and impacts tumor proliferation." (PMID 29099049, 2017). "Semi quantitative PCR confirmed higher expressions of AR and KLK3 genes in tumor tissues compared to that in the BPH sample, which was considered as a reference control in the microarray experiment." (PMID 28852180, 2017). "After treatment with berberine, the expression of PSA, AR, COX-2 and Bcl-2 were significantly reduced and the expression of Caspase-3 was significantly increased in tumor samples." (PMID 29029409, 2017). "Due to the inherent dependency of prostate tumors on the AR, the primary anti-tumor effect of ADT is a result of directly inducing tumor cell apoptosis." (PMID 28134800, 2017). "We analysed AR CN from plasma samples using digital PCR and Taqman CN assays and total lesion activity (TLA) and metabolic tumor volume (MTV) on FCH-PET/CT at baseline." (PMID 29138500, 2017). "The AR and miR-21 axis negatively alters the TGFBR2 pathway, and in this way inhibits the tumor-suppressive activity of TGFβ." (PMID 28275218, 2017). "For example, the AR signaling pathway has long been thought to play a critical role in TNBC and to likely be relevant to tumor metastasis." (PMID 28583190, 2017). "To explore the functions of ERβ1 on tumor metastasis in AR-positive TNBC, we transfected two AR-positive TNBC cell lines, MDA-MB-231 and Hs578T, with the empty vector or the ERβ1 expression vector." (PMID 28583190, 2017). "These phenomena further support the idea that AR reactivation in CRPC progression requires enhanced redox-protective pathways, notably TRX1, as a tumor-promoting adaptive response." (PMID 29089489, 2017). "Amplification of AR-FL, ARV7, and ARv567es transcripts by quantitative RT-PCR with cDNA made using 69 metastatic CR-PCa tumor samples from 13 patients showed that 46 samples were positive for AR-FL or either ARV." (PMID 28077788, 2017). "In the cytosol, the AR NTD has the potential to activate Src and PI3K, to drive tumor growth and survival." (PMID 28144231, 2017). "In our motif searches, the validated AR-cooperating transcription factor FOXA1 displayed motif enrichment, differential up-regulation, and high tumor expression, serving as test and validation data point." (PMID 27623747, 2016).
tumor (continued). "Following the Smad signaling mediators, the down-regulation of AR consequentially activated target genes like matrix metallopeptidase 9 (MMP-9) and promote tumor metastasis." (PMID 27703473, 2016). "A combination of sulforaphane, bicalutamide, and enzalutamide enhanced the anti-proliferative effects, decreased tumor cell migration, and reduced PSA and AR expression in LNCaP and C4-2B cells." (PMID 27651838, 2016). "The lack of tumour-specific AR-V expression in tumours C-14A and C-14B highlights the possibility that AR-GSRs present at low variant allele fraction may simply reflect bystander events resulting from the AR gene amplification process and/or a high burden of genomic rearrangements in CRPC24." (PMID 27897170, 2016). "For example, AR in L(-)ID4 cells and prostate epithelial cells from Id4−/− mice fails to express NKX3.1 (a homeodomain protein), an androgen activated PCa tumor suppressor." (PMID 27487149, 2016). "AR amplification is a common feature of CRPC, and upregulation of the androgen synthetic machinery is an emergent resistance mechanism in CRPC tumor cells to overcome androgen deprivation therapies." (PMID 27276681, 2016). "Androgen receptor (AR) antagonist MDV3100 is the first therapeutic approach in treating castration-resistant prostate cancer (CRPC), but tumours frequently become drug resistant via multiple mechanisms including AR amplification and mutation." (PMID 27959342, 2016). "Over-expression of GRP78 prevented AR-12 induced PERK activation; autophagy induction, and tumor cell killing." (PMID 26887051, 2016). "In order to characterize the relationship between AR and CD90 expression in HCC, we examined their expression levels at various stages of tumor development in a spontaneous HCC mouse model." (PMID 27340775, 2016). "In any event, we conclude that salinomycin can potentially lower tumor cell androgen levels by inhibiting CYP17A1 and HSD3β1, thereby further restricting AR signaling." (PMID 27557496, 2016). "In addition, the absence of AR expression in long CAG repeat sequences was associated with tumour size larger than 5 cm in diameter, which were moderate to poorly differentiated (at T3–T4 and N1–2 stages) compared to those with normal expression of AR and short CAG repeat sequences." (PMID 27833666, 2016). "Although recent studies have identified a few established cancer pathways regulating AR activity in CRPC, such as WNT and PI3K, the landscape of molecular pathways controlling ligand-independent AR function and tumor growth remains undetermined." (PMID 27363033, 2016). "Other targets of SPOP include the AR and the ERG oncogene, confirming the importance of this gene in driving tumour progression." (PMID 27408704, 2016). "Although AR overexpression was present in progressive HCC, AR was also found to be essential in suppressing HCC metastasis in the later stage of tumor development." (PMID 27703473, 2016). "Recently, exposure of enzalutamide-resistant mCRPC cells to BETi (JQ1 and OTX015) resulted in attenuation of AR target genes (FKBP5, KLK3, ERG, and MYC) and AR-v7 expression as well as decreased CRPC cell proliferation in vitro and tumor growth in vivo." (PMID 27651838, 2016). "Abiraterone suppresses synthesis of androgens from the adrenal gland and tumor cells via CYP17 inhibition and has also been found to interfere directly with ligand binding to the AR." (PMID 27276681, 2016). "Further analysis of the excised tumor xenografts confirmed a tendency towards decreased CHKA levels and clearly decreased AR protein expression in CHKA sh#2 xenografts from mice treated with doxycycline (available online)." (PMID 26657335, 2016). "However, the mechanisms whereby AR regulates growth suppression and differentiation of luminal epithelial cells in the prostate gland and proliferation of malignant versions of these cells are not well understood, though they are central to prostate development, homeostasis, and neoplasia." (PMID 26372468, 2015).
tumor (continued). "Preclinical studies have shown that JQ1 disrupts AR-mediated gene transcription in CRPC models, significantly reducing tumour volume relative to controls." (PMID 25896606, 2015). "In fact, in the modern era of effective AR axis inhibition at different stages of progression, it is now relatively common to find late-stage CRPC where the AR has become incidental to a tumour's successful growth and evolution." (PMID 25896606, 2015). "Since AR and its interactors were enriched at FAIRE-seq regions (Fig2G), we next performed AR ChIP-seq on five primary and three treatment-resistant tumor specimens (Fig3A)." (PMID 26412853, 2015). "The expression of AR targeted genes including PSA, TMPRSS2 and UBE2C as well as the tumor proliferation index Ki67 were more strongly inhibited by ENZ plus ICRF187." (PMID 26009876, 2015). "The growth inhibition effects of wedelolactone on tumor cells were believed to be accomplished through its inhibition of IKK, the androgen receptor, or topoisomerase II." (PMID 25944687, 2015). "Knock-down of the AR decreased the serum PSA value, inhibited tumor growth, and resulted in tumor regression, in the castration resistant state." (PMID 25793207, 2015). "In order to determine the expression of miR-190a, AR, YB-1, CDKN1A, and Ki-67 in tumor tissues, we conducted RT-PCR and IHC staining on tumor samples." (PMID 26314494, 2015). "Our results further indicated that co-treatment of Topo II inhibitors with ENZ results in stronger suppression to AR signaling and CRPC cell growth and tumor growth." (PMID 26009876, 2015). "Therefore, future studies should extend our cell culture analysis to assess the AR-mediated regulation of these ARGs and their relative contribution to epithelial cell proliferation in developing and adult prostate tissue, and during neoplastic disease progression in the prostate." (PMID 26372468, 2015). "The tumor cells were positive for EGFR (3+), AR (strongly positive) HER-2 expression (2+) by immunohistochemistry." (PMID 25699235, 2015). "To ensure that our xenograft models retained typical features of their respective subtype, we assessed expression of molecular markers specific to PCa (AR, PSA) and NEPC (SYP, CHGA) in the investigated Living Tumor Lab (LTL) tumor lines." (PMID 25859291, 2015). "The existence of AR+;PSA− and AR−;PSA+ tumor cells in both primary and CRPC samples has been recently confirmed." (PMID 26593949, 2015). "The expression levels of AR, MMP-2 and MMP-9 in HCC tissues and tissues adjacent to the tumor were measured by immunohistochemical staining assay." (PMID 25667651, 2015). "The effects of gal and VNPT55 were analyzed on f-AR and AR-Vs (AR-V7/ARv567es) in LNCaP, CWR22Rv1 and DU145 (transfected with AR-Vs) human PC cells in vitro and CRPC tumor xenografts." (PMID 26196320, 2015). "The most highly correlated gene was BRINP1 which has been shown to influence the rate of proliferation in tumour cell lines, in part by modulating the activities of the steroid and retinoic acid receptors ERA, AR and RARA." (PMID 26479384, 2015). "Based on the results from 2-dimensional and 3-dimensional cell culture models, we investigated the effect of combined targeting of AR and PI3K in vivo in LAR cell line-derived tumor xenografts." (PMID 25103565, 2014). "Our results suggest that transcription factors E2F4, AR and ETS1 are potential key regulators in tumour progression." (PMID 24523864, 2014). "Overexpression of CAM2KN1 in DU145 tumor tissues resulted in decreased ErbB2, AKT1, Bcl-2, NF-κB and AR mRNA levels and increased p21, Bax mRNA levels." (PMID 25003983, 2014). "We performed Western blot analysis on tumor cell lysates and carried out chromatin-immuno-precipitation (CHIP) after AR overexpression." (PMID 25510351, 2014).